MMP2 (matrix metallopeptidase 2)
Diseases named in the same sentence as MMP2 in open-access papers (continued):
Sharing a sentence is not in itself a finding about the gene and the disease.
ischemia (79 papers, 2005 to 2025). A hypoperfusion of the BLOOD through an organ or tissue caused by a PATHOLOGIC CONSTRICTION or obstruction of its BLOOD VESSELS, or an absence of BLOOD CIRCULATION. "ONO-4817 a selective inhibitor, has shown beneficial results in an ischemia and reperfusion model, improving contractile dysfunction, associated with decreased MMP-2 activity and titin proteolysis." (PMID 35893744, 2022). "The early degradation of tight junction (TJ) proteins appears to be associated with MMP-2 in the early period of ischemia, and direct injection of MMP-2 into the rat brain disrupts the BBB." (PMID 30572925, 2018). "In a hypertensive rat model, induced ischemia causes increased MMP-2 secretion and degradation claudin-5 and occludin in endothelial tight junctions, leading to breakdown of the blood-brain barrier." (PMID 25412440, 2014). "Here, the involvement of AP-1 site in the transcriptional regulation of MMP-2 is associated with cardiac cellular response to damaging stress, such as ischemia and infarction leading to the ventricular remodelling process." (PMID 24195673, 2013). "The first main finding of the present study was the ability of hyperoxia to reverse the (in controls positively directed) association of BBB permeability, MMP-2 and -9 when administered 2 hours after ischemia onset." (PMID 22273146, 2012). "It was previously found that pharmacological inhibition of MMP-2 may reduce injury caused by ischemia and reperfusion." (PMID 36082193, 2022). "Thus, the aim of the current study was to investigate the potential protective effects against the deregulatory and detrimental effects of MMP-2 and collagen content, linked with the detection of necrotic ratio after ischemia/reperfusion injury." (PMID 29636852, 2018). "Our findings suggest a possible connection between MMP activities and ischemia/reperfusion induced cardiac damage, supporting the idea that low MMP-2/9 activities may be associated with reduced ischemia/reperfusion injury." (PMID 24712447, 2014). "We have previously shown that MMPs and the RhoA/ROCK pathway inhibitor simvastatin have a protective effect on cardiac systolic function in an acute ischemia–reperfusion model by inhibiting the RhoA pathway independently of reducing MMP-2 activity." (PMID 38540212, 2024). "The second protein is myosin light chain (MLC), which is modified during acute ischemia and degraded by MMP-2." (PMID 38672140, 2024). "Intracoronary administration of the Doxy, ML-7, and L-NAME mixture during ischemia led to a decrease in MMP-2 (p = 0.0134), MMP-9 (p = 0.017), MLC1 (p = 0.003), and BNP-26 (p = 0.002) concentrations in the blood as compared to the MI." (PMID 38672140, 2024). "The duration of ischemia and r-tPA treatment also significantly increased MMP-2 expression (p < 0.01–0.001) in the ischemic hemisphere (p < 0.01) but to a lesser degree than MMP-9." (PMID 39273389, 2024). "A study looking into changes in the vasculature microenvironment found that, after 3 days of ischemia, MMP-2, MMP-3, and MMP-13 levels were elevated in diabetic mice compared to non-diabetics." (PMID 36745438, 2023). "Elevated ECF-Zn during ischemia directly bound to MMP-2 in extracellular fluid, increased its zinc content and augmented MMP-2 activity, leading to the degradation of tight junction protein in cerebral microvessels and BBB disruption." (PMID 37962463, 2023). "In the current study, we investigated how the administration of MMP-2 siRNA affected hearts subjected to ischemia/reperfusion injury." (PMID 36082193, 2022). "Authors reported that protein expression of dimeric MMP-9 forms was highly stimulated (about 8-fold) by ischemia, compared to the expression of MMP-2 (1.5-fold)." (PMID 35631351, 2022). "MMP-2, on the other hand, is important in the later stages of ischemia, during the formation of glial scar within the damaged area." (PMID 34299128, 2021).
ischemia (continued). "There are also studies indicating that increased expression of MMP-2 exists in experimental models of renal injury during ischemia." (PMID 31936869, 2020). "Activation of matrix metalloproteinases (MMPs) in the brain after ischemia has been reported, including increased expression of constitutive enzymes (MMP-2) and inducible enzymes (MMP-9)." (PMID 32796743, 2020). "MMP-2 and MMP-9 have been associated with the proliferation and migration of EPCs in ischemia-induced angiogenesis." (PMID 30645596, 2019). "Compared with MMP‐9, the expression of MMP‐2 lagged behind and peaked on the fifth day after ischemia." (PMID 31566928, 2019). "We found that MMP-2 expression and zymographic activity were lower in TG hearts than in WT hearts after ischemia, consistent with the inverted M1/M2 balance found in these animals." (PMID 29445778, 2017). "In conclusion, the present study revealed that AMI induces MMP-2 release, which hampered the ischemia-induced increase in SDF-1α and CXCR4 by cleaving the SDF-1α/CXCR4 axis." (PMID 28299177, 2016). "One discrete matrix metalloproteinase, matrix metalloproteinase-2 (MMP-2) has been the focus of considerable attention in rodent models of ischemia/reperfusion injury." (PMID 26379248, 2015). "The release of MMP-2 peaked during the first and fifth minutes of reperfusion and was enhanced with increasing duration of ischemia." (PMID 25874025, 2015). "The release of MMP-2 increases with increasing duration of ischemia and correlates negatively with functional recovery." (PMID 25874025, 2015). "This increased level of the truncated form of MLC1 was negatively correlated with recovery and positively correlated with increased MMP-2 activity, which was correlated with the duration of ischemia." (PMID 24455428, 2013). "Previously we found that CIB1, a 22 kDa regulatory protein, plays a critical role in endothelial cell function, angiogenic growth factor-mediated cellular functions, PAK1 activation, MMP-2 expression, and in vivo ischemia-induced angiogenesis." (PMID 20804551, 2010). "There was no significant change in ZO-1 expression (a tight junction protein modulated by MMP-9) between control and cKO mice in response to 2h-ischemia/4h-reperfusion, indicating the critical role of MMP-2/occludin pathway in neuronal ZnT3-modulaed BBB disruption in response to cerebral ischemia." (PMID 37962463, 2023). "We hypothesized that ischemia-released ECF-Zn may directly activate MMP-2/-9 in extracellular fluid (ECF-MMP-2/-9)." (PMID 37962463, 2023). "Thus, the main aim of the study was to investigate the effect of MMP-2 siRNA administration on heart subjected to ischemia/reperfusion injury." (PMID 36082193, 2022). "This study investigated whether another RhoA/ROCK signaling pathway inhibitor, simvastatin, decreased MMP-2 activity in a rat model of ischemia-reperfusion injury by inhibiting the RhoA/ROCK pathway and reducing MMP-2 mRNA levels." (PMID 36139129, 2022). "Our findings are limited because we did not include the various phases of ischemic stroke; however, we observed that carnosine treatment at 3 h after ischemic onset significantly reduced MMP-2 activity, inhibiting edema and cerebral infarction determined at 24 h after ischemia." (PMID 34299128, 2021). "Moreover, MMP2 expression is disrupted in ischemia/reperfusion injury models, thereby leading to contractile dysfunction." (PMID 32600379, 2020). "However, exercise-induced cardiac remodeling serves as a compensatory mechanism by enhancing MMP-2 activity and reducing fibrosis, thus minimizing the ischemia/reperfusion injury." (PMID 29636852, 2018). "The levels of MMP-2/9 were analyzed with gel zymography after 2-h of ischemia." (PMID 30233326, 2018). "The findings in this study may provide clues for developing new treatment strategies to protect the ECM of vessels against degradation induced by MMP2 and 9 and thus safely expand tPA thrombolytic therapy for ischemia." (PMID 26881424, 2016).
ischemia (continued). "Finally, MMP-2 has been shown to be involved in renal ischemia-reperfusion injury in an animal model whereby warm ischemia was induced in situ for 30 to 120 minutes in an MMP-2 deficient transgenic mouse model." (PMID 27327879, 2016). "EphA4 also negatively regulates EC expression of angiopoietin-1, MCP-1 and MMP2 which may have a profound effect on collateral density during development and/or remodeling following ischemia." (PMID 27467069, 2016). "Activated MMP-2 degrades susceptible sarcomeric and cytoskeletal proteins including troponin I (TnI), myosin light chain-1 (MLC-1), and α-actin, leading to the acute contractile dysfunction observed in ischemia/reperfusion injury." (PMID 25559243, 2015). "Experimental studies have demonstrated that ischemia/reperfusion injury induces the synthesis of the full length secreted isoform of matrix metalloproteinase-2 (FL-MMP-2), as well as an intracellular N-terminal truncated MMP-2 isoform (NTT-MMP-2) that initiates an innate immune response." (PMID 26379248, 2015). "In this context, early MMP-2 elevation after ischemia might be beneficial because MMP-2 is a crucial protease involved in blood vessel remodeling through angiogenesis." (PMID 26637168, 2015). "However, the role of MMP-2 in ischemia was reported in adult models, in which its rapid elevation mediated BBB impairments." (PMID 23940734, 2013). "While gelatinase (MMP-2 and -9) activity is increased after focal ischemia/reperfusion injury in the brain, the relative contribution of neutrophils to the MMP activity and to the development of hemorrhagic transformation remains unknown." (PMID 16078993, 2005). "Moreover, it has been observed that MMP-2 inhibitors may reduce TnI degradation in the myocardium after ischemia reperfusion injury process." (PMID 22204652, 2011). "The focus of the present study was to determine the time-dependent effects of the duration of ischemia and r-tPA treatment on brain injury, neurobehavioral outcomes, and the expression of MMPs (MMP-9, MMP-2, and MMP-3) in cerebral ischemia with reperfusion." (PMID 39273389, 2024). "MMP-2 immunoexpression was strong both in the stroma and the cardiac muscle fibers, suggesting an ongoing reaction of the ECM following injury and ischemia." (PMID 39682376, 2024). "The right atrial activity of reperfused myocardium was followed, showing a rapid increase in MMP2 and MMP9 activity accompanied by a rapid decrease in TIMP1, demonstrating global alteration of left ventricular function and persistence of ischemia." (PMID 37512106, 2023). "In our experiments, we observed elevated MMP2 and MMP9 expression after lung ischemia–reperfusion at the tissue level in three separate organisms: human, rat, and mouse." (PMID 35705936, 2022). "To initially explore the relationship of MMP2 and MMP9 with lung ischemia–reperfusion injury, we performed relevant bioinformatics analysis using the GEO database." (PMID 35705936, 2022). "Here, the effects of OCA on MMP-2 and MMP-9 activity in liver, bile and serum were evaluated after hepatic ischemia/reperfusion (I/R) injury." (PMID 32911524, 2020). "Overexpression of MMP-2 and MMP-9 can digest basal lamina, and this digestion begins as early as 2 h following ischemia, which corresponds with BBB breakdown 3 h following ischemia." (PMID 31291966, 2019). "Astrocytes activated by ischemia and anoxia secrete many pro- and anti-inflammatory factors, such as IL-1β, IL-6, TNF-α, TGF-β, VEGF-A, MCP-1 CXCL-1, MMP-2, and MMP-9, which influence BBB integrity." (PMID 31779652, 2019). "In conclusion, both redox-related MMP-2 and MMP-9 activation are critical to the function of EPCs for in vivo ischemia-induced angiogenesis." (PMID 30645596, 2019). "Our results showed that ischemia produced BBB damage and MMP-2/9 upregulation was colocalized with Rhodamine-dextran leakage." (PMID 30233326, 2018).
ischemia (continued). "Inhibition of HIF-1α reduced blood-brain-barrier (BBB) damage after 2-h ischemia in a rat model of focal cerebral ischemia, and its downstream vascular endothelial growth factor (VEGF) and matrix metalloproteinase-2/9 (MMP-2/9)." (PMID 30647760, 2018). "We made a similar observation in a hind limb ischemia model, where MMP-2 and MMP-9 activity were decreased in Poldip2+/− mice when compared to Poldip2+/+ mice 21 days after ischemia." (PMID 29452577, 2018). "In accordance with other studies, our data showed that protein levels of MMP-2 and MMP-9 were induced in an ischemia time-dependent manner, and this change was accompanied by the loss of TJPs occludin and claudin-5." (PMID 29850586, 2018). "Previous studies showed that 2-h ischemia induced damage of BBB integrity and matrix metalloproteinase-2 (MMP-2) made major contribution to this disruption." (PMID 30233326, 2018). "We propose that ischemia-induced NO initiates S-nitrosylation of Cav-1, and tPA-activated ERK signal pathway stimulates the expression of MMP2 and 9 and shedding of S-nitrosylated Cav-1." (PMID 26881424, 2016). "As expected, MMP-2 and MMP-9 levels were elevated in injured ipsilateral brain tissue in all ischemia and hemorrhage mice." (PMID 23408937, 2013). "In conclusion, we demonstrated the effects of running on MMP2 upregulation and VEGF production in rats’ ischemia brain tissue." (PMID 23598418, 2013). "The expression of matrix metalloproteinase 2 (MMP2) and vascular endothelial growth factor (VEGF)-related genes and proteins were higher over time post-ischemia, and exercise enhanced their expression." (PMID 23598418, 2013). "Up-regulated MMPs, especially MMP-2 and MMP-9, have been detected following acute kidney injury, mostly in animal models of ischemia, and up-regulation of MMP-9 was reported to protect from apoptosis in AKI." (PMID 22509332, 2012). "Levels of MMP-2 and MMP-9 are significantly elevated following ischemia, brain injury, and kainate treatment, implying a role for MMP-2 and MMP-9 in remodeling of neural circuits in response to neural activity and brain damages." (PMID 22567285, 2012). "Among the main differences between their molecular pathways, MMP-2 is constitutively expressed, while MMP-9 can be stimulated at the level of gene activation by multiple stimuli including ischemia." (PMID 16846501, 2006). "While carnosine significantly reduced MMP-2 activity post-ischemia in rat brain homogenates, there was no statistically significant reduction in MMP-9 activity." (PMID 34299128, 2021). "The activity of MMP9 and MMP2 can break down the BBB via directly degrading tight junction proteins such as occludin and claudin-5, leading to reversible degradation early after the onset of ischemia and initiating vasogenic edema." (PMID 32221863, 2021). "Importantly, PCB treatment abolished MMP-2 and MMP-9 induction in the ischemic tissue of t-PA-treated rats following 2 to 8 hr ischemia." (PMID 29850586, 2018). "Our previous finding showed that BBB damage is mediated by secreted but not new synthesized MMP-2 at a very stage of ischemia has led us to investigate the factors that induces MMP-2 secretion." (PMID 28855859, 2017). "Non-conditioned AMI induces MMP-2 release, hampering the ischemia-induced increase in SDF-1α and CXCR4 by cleaving the SDF-1α/CXCR4 axis, with diminished mobilization of the angiogenic CD34+ cells." (PMID 28299177, 2016). "In addition to the induction of pro-inflammatory factors, NF-κB also increases the secretion of MMP-2 and MMP-9, whose levels are increased in the reperfused myocardium after ischemia." (PMID 25084093, 2014). "In our most recent work using isolated cardiomyocytes subjected to 60 minutes of simulated ischemia, ONOO−-modified MLC1 increased degradation of MLC1 by MMP-2, and ONOO− scavengers protected cardiomyocytes from contractile dysfunction triggered by oxidative stress." (PMID 24455428, 2013).
ischemia (continued). "While there were significant increases in gelatinase (MMP-2 and MMP-9) expression and activity and edema formation associated with ischemia, neutrophil depletion failed to cause any change." (PMID 16078993, 2005). "Recent studies showed that 2-h ischemia caused damage of BBB integrity in non-infarcted ventromedial striatum and 2-h ischemia-induced matrix metalloproteinase-2 (MMP-2) induction lead to the disruption of the BBB integrity." (PMID 30233326, 2018). "However, it is not clear about the interaction of HIF-1α with MMP-2 in BBB damage during acute ischemia." (PMID 30233326, 2018).